APC (APC regulator of Wnt signaling pathway)
Diseases named in the same sentence as APC in open-access papers (continued):
Sharing a sentence is not in itself a finding about the gene and the disease.
desmoid tumor (57 papers, 2003 to 2026). A desmoid tumor (DT) is a benign, locally invasive soft tissue tumor associated with a high recurrence rate but with no metastatic potential. "Patients with the APC (c.1744-1G > A) mutation appear to develop symptoms later, exhibit a low risk of desmoid tumors, and carry a higher risk for rectal cancer." (PMID 39985003, 2025). "Nuclear beta-catenin and point mutation of CTNNB1 can also be identified in desmoid fibromatosis and other Gardner syndrome APC/Wnt-pathway tumors." (PMID 39093425, 2025). "Mutations in CTNNB1 or APC genes can lead to abnormal intracellular accumulation of β-catenin, a hallmark of desmoid-type fibromatosis." (PMID 41367864, 2025). "About 10%–15% of desmoid tumors are due to germline mutations in the APC (adenomatous polyposis coli) gene." (PMID 39296517, 2024). "FAP-associated tumors tend to appear earlier than sporadic desmoid tumors, and their appearance is correlated with the location of the APC." (PMID 35158896, 2022). "Still, the most acknowledged risk factor is the association with FAP, which increases by 1000-fold the risk for developing desmoid tumors, in patients with Gardner syndrome and a germline mutation of the APC gene, a component of the Wnt pathway." (PMID 35800111, 2022). "Here we report the detection of a somatic mosaic APC mutation in a patient who was diagnosed with desmoid type fibromatosis in childhood." (PMID 29368261, 2018). "This case report presents the detection of a mosaic APC mutation in a 26-year-old woman who as a child had been diagnosed with desmoid type fibromatosis." (PMID 29368261, 2018). "Extracolonic manisfestations were rarely reported, but three of the four Gardner syndrome cases described here (diagnosed with multiple adenomas together with desmoid tumors) were found to carry an inactivating APC mutation after codon 1400." (PMID 26446593, 2016). "Desmoid tumors in FAP are typically associated with mutations in the APC gene located downstream of codon 1400." (PMID 26940557, 2016). "We compared the prevalence of APC mutations in the published patients with desmoid tumors to the prevalence of the same mutation in the reference population." (PMID 26179480, 2015). "It is noteworthy that our search revealed only 274 published patients with FAP, a specified APC gene mutation, and desmoid tumors." (PMID 26179480, 2015). "We believe that this is the largest group of pooled cases that includes desmoid tumors and APC gene mutations reported to date." (PMID 26179480, 2015). "When comparing our desmoid tumor database to previously published APC gene mutations, our database was able to be broken down into 7 regions of the APC gene." (PMID 26179480, 2015). "The aim of this study is to better define the correlation between APC gene mutations and desmoid tumor formation." (PMID 26179480, 2015). "There is an increased risk for desmoid tumors in individuals with APC mutations between codons 543-713 and 1310-2011 when compared to a reference population." (PMID 26179480, 2015). "For instance, in our series, desmoid tumors were much more prevalent in APC-mutated patients (57%) than in others previous studies (10-15%), indicating that perhaps our set of patients represents a distinct group regarding this extracolonic feature." (PMID 23561487, 2013). "Approximately 12% to 25% of patients with inherited mutations in APC (familial adenomatous polyposis, Gardner’s syndrome) will eventually develop a desmoid tumor." (PMID 24213241, 2012). "In contrast, sporadic desmoid tumors rarely have somatic mutations in APC; direct mutations in beta-catenin are more common." (PMID 24213241, 2012). "Desmoid tumors associated with familial adenomatous polyposis (FAP) have been shown to be associated with mutations in the adenomatous polyposis coli (APC) gene." (PMID 24212949, 2011).
desmoid tumor (continued). "One of them, CHRPE, only occurs in patients with germline APC mutations between codons 457 and 1444, and desmoid tumors develop only in patients having mutations between codons 1403 and 1578." (PMID 21078199, 2010). "Some other recent papers have also reported the occurrence of desmoid tumors in FAP patients with APC mutations outside the region between codons 1403 and 1578." (PMID 21078199, 2010). "Desmoid tumors are common in patients with familial adenomatous polyposis, an autosomal inherited disease caused by a genetic mutation in the APC (adenomatous polyposis coli) tumor suppressor gene, which is known to be a tumor suppressor gene." (PMID 20011031, 2009). "Recently, It was found that virtually all desmoid tumors have somatic [beta]-catenin or adenomatous polyposis coli (APC) gene mutation leading to intranuclear accumulation of [beta]-catenin." (PMID 18312655, 2008). "A clear genotype–phenotype relationship exists: APC mutations between codons 1445 and 1578 are associated with an increased risk of desmoid tumors—patients with attenuated FAP usually have mutations at the 5′ (proximal to codon 1517) or the 3′ end (distal to codon 1900) of the APC gene." (PMID 36672501, 2023). "Because of the association of MB and desmoid fibromatosis, an APC germline mutation was suspected." (PMID 35978432, 2022). "Desmoid-type fibromatosis might be one of the manifestations of the APC gene linked FAP but they are generally sporadic tumors." (PMID 26056602, 2015). "Furthermore, besides the location of APC mutations, several other risk factors are suggested to be related with desmoid tumor development, such as surgical trauma, pregnancy and especially positive family history for desmoid tumors." (PMID 23561487, 2013). "Desmoid tumors are rare neoplastic tumors that may occur sporadically or in association with FAP caused by a germline mutation in the APC gene." (PMID 23575352, 2013). "Most APC mutations associated with desmoid tumors are found 3′ to codon 1400." (PMID 21403834, 2011). "In FAP, desmoid tumors arise from mutations in the adenomatous polyposis coli (APC) gene, located on chromosome 5q21-22, which encodes a tumor suppressor protein, although its function may be more complex than simply a tumor suppressor." (PMID 21403834, 2011). "The pathogenesis of desmoid tumors is uncertain and may be related to trauma, hormonal factors, or a mutation in the APC gene." (PMID 20011031, 2009). "The pathogenesis of desmoid tumors is uncertain and may be related to trauma, hormonal factors, or mutation in the APC gene." (PMID 20011031, 2009). "However, this is the first analysis that attempts to define the actual risk of desmoid tumors based on specific APC gene mutations while adjusting for the frequency distribution of APC mutations in an FAP reference population, in an attempt to obviate bias toward more common mutations." (PMID 26179480, 2015). "They highlighted the evidence of Wnt signaling pathway involvement, APC, and β-catenin in desmoid tumors." (PMID 37623452, 2023). "We found that desmoid tumors harbor mutations in CTNNB1, APC, and GNAQ, all of which are associated with pathological activities." (PMID 36497457, 2022). "Similar to desmoid tumors and hepatoblastoma, somatic CTNNB1 mutations are common in sporadic hepatoblastoma (50–90% of patients) and likely mutually exclusive with germline APC mutations, although further research is needed." (PMID 35158896, 2022). "Desmoid fibromatosis has been reported to carry CTNNB1 mutations in up to 89% of sporadic cases, while APC mutations have only rarely been detected in the sporadic context." (PMID 34725446, 2022). "Aggressive fibromatosis (AF) is a rare fibroblastic proliferative disease characterized by driver mutations in CTNNB1, at specific sites of exon 3, or in the APC gene (in the context of Gardner syndrome)." (PMID 25174682, 2014).
desmoid tumor (continued). "It has been reported that dysregulation of the Wnt-adenomatous polyposis coli (APC)-β-catenin signaling cascade plays a key role in the pathogenesis of sporadic desmoid tumor." (PMID 23575352, 2013). "Inheritance (or new mutation) of one copy of APC tumor suppressor gene is the cause of FAP and the two commonest causes of deaths in these patients are duodenal cancer and desmoid tumors." (PMID 21426541, 2011). "The pathogenic APC p.R283* truncating mutation was detected as second somatic hit in MB, establishing it as FAP-associated MB-WNT, whereas the APC locus showed homozygous CN loss in the desmoid fibromatosis." (PMID 35978432, 2022). "Thus, both CTNNB1/APC and GNAQ mutations have been associated with increased TGF-β signaling in fibroblasts, and monoclonal proliferation can lead to desmoid tumors." (PMID 36497457, 2022). "Otherwise, some studies have suggested the likelihood that specific modifier genes exist, independent of APC, whose variation increases the risk of desmoid tumors in FAP patients." (PMID 29954149, 2018). "Aggressive fibromatosis (AF) is a rare fibroblastic proliferative disease with a locally aggressive behavior and no distant metastasis, characterized by driver mutations in CTNNB1 or the APC gene." (PMID 25174682, 2014). "Although the etiology of desmoid tumors remains unknown, increasing evidence points to involvement of the APC gene and beta-catenin in the molecular pathogenesis of inherited desmoids (Gardner's syndrome) as well as in sporadic cases." (PMID 23346436, 2013). "Indeed, desmoid tumors represent the second leading cause of death in FAP patients and were identified at high frequency in our cohort, occurring in 57% (8/14) of APC-mutated families." (PMID 23561487, 2013). "Although molecular testing for CTNNB1 or APC mutations was not performed due to the emergent nature of the surgery, the combined histomorphological and immunohistochemical findings definitively established the diagnosis of desmoid-type fibromatosis." (PMID 41367864, 2025). "In a combined analysis in 60 APC mutation carriers and their 58 untested relatives with FAP associated cancer or benign manifestation, the phenotypic features observed were 79 CRC, 5 upper GI cancers, 3 thyroid cancer, 2 brain tumors, 13 desmoid tumors/fibromatosis." (PMID 28533537, 2017). "Furthermore, three relatives had developed a desmoid tumor, usually not observed in patients with a mutation at the 5′ end of the APC gene." (PMID 23561487, 2013). "In keeping with published studies, there were frequent mutations of BRAF and NRAS in melanoma; BRAF, EGFR, KRAS, and STK11 in NSCLC; APC, BRAF, KRAS, and PIK3CA in CRC; KIT and PDGFR3A in GIST; and CTNNB1 in other tumours (desmoid fibromatosis)." (PMID 28196074, 2017). "However, unknown genetic factors independent of APC may be important in the susceptibility to desmoid tumors in patients with FAP." (PMID 26889339, 2015).
pancreatic cancer (54 papers, 2010 to 2026). "Among studied genes, KRAS in GC and pancreatic cancer and APC in CRC had the most association with cancer outcome." (PMID 33127962, 2020). "The loss of APC was observed to accelerate the formation of pancreatic cancer, with the metastasis rate being significantly higher than PKP model." (PMID 32586050, 2020). "Given the lack of effective treatment strategies for pancreatic cancer, it is important to understand the functional implications of APC loss in pancreatic cancer cell lines." (PMID 31540078, 2019). "It is important to understand the functional implications of APC loss in pancreatic cancer cells lines." (PMID 31540078, 2019). "Given the variable results observed in different cell lines, future studies would be necessary to understand the crosstalk between APC loss and other drivers of pancreatic cancer." (PMID 31540078, 2019). "The current study sought an association between four different CD24 SNPs, two APC genetic variants, and the clinical course of pancreatic cancer." (PMID 26394139, 2015). "Because PI3K inhibition blocked WNT activation in APC mutated colon and pancreatic cancer cells, we propose an association of PI3K signaling and WNT signaling in CC and other malignancies." (PMID 24930890, 2014). "Another group of investigators hypothesised that APC mutation may play a role in the initiation of pancreatic cancer." (PMID 36765737, 2023). "Therefore, familial pancreatic cancer has a wide range of germline variants instead of a predominant gene such as BRCA1/2 in HBOC or APC in FAP." (PMID 34476650, 2021). "Hypermethylation of APC promoters associated with prognosis in pancreatic cancer." (PMID 33968756, 2021). "Variants in APC would induce various kinds of cancer, such as colorectal and pancreatic cancers." (PMID 34107880, 2021). "It is still unknown whether DKK2 plays similar roles in other cancer types with reoccurring APC mutations, such as pancreatic cancer." (PMID 31372243, 2019). "Our research investigates whether APC loss in pancreatic cancer mediates in vitro tumorigenic potential." (PMID 31540078, 2019). "In another study, somatic mutations in APC were observed in 4 of 10 pancreatic tumors examined." (PMID 31540078, 2019). "It is important to understand the functional implications of APC loss in pancreatic cancer cells lines, which could be used as a target for therapeutics." (PMID 31540078, 2019). "APC, a well‐known tumor suppressor, is a key component of the Wnt/β‐catenin signaling pathway, which is frequently dysregulated in pancreatic cancer, leading to aberrant cell growth and survival." (PMID 40952239, 2025). "Further emphasizing the role of CAFs in cancer progression, exosomal miR-125b-5p facilitates pancreatic cancer cell growth, migration, and invasion by suppressing the expression of the adenomatous polyposis coli (APC) gene, a known tumor suppressor." (PMID 38954230, 2024).
pancreatic cancer (continued). "P/LP variants of APC, BRCA2, BUB1B and ENG were identified in patients with pancreatic cancer, and MSH6 was identified in an NPaMC patient with both colorectal and esophageal cancers." (PMID 36896836, 2023). "Tier I or II mutations related to hereditary cancer syndrome in pancreatic cancer were identified in BRCA1 (n = 2, 2.3%), BRCA2 (n = 2, 2.3%), PRSS1 (n = 1, 1.1%), MSH6 (n = 2, 2.3%), PMS2 (n = 1, 1.1%), and APC (n = 1, 1.1%)." (PMID 36463295, 2022). "Pancreatic cancer onset in FAP patients is rare, representing about 1% of extracolonic malignancies; today, few germline APC mutations have been found in FPC patients." (PMID 35205366, 2022). "Compared with other GI cancers, less attention has been paid on the correlation between APC promoter methylation and pancreatic cancer." (PMID 33968756, 2021). "A number of early studies found that the frequency of APC promoter CpG island hypermethylation was quite distinguished and was detected in 58.6 to 71% of patients with pancreatic cancer." (PMID 33968756, 2021). "For example, the miRNA-205 level was found to be significantly higher in pancreatic cancer patients; it promotes the proliferation of pancreatic cancer cells by targeting APC." (PMID 33178832, 2020). "Using lentiviral shRNA, we successfully knocked down APC expression in six pancreatic cancer cell lines (AsPC-1, BxPC3, L3.6pl, HPAF-II, Hs 766T, MIA PaCa-2)." (PMID 31540078, 2019). "APC is lost in a subset of pancreatic cancers, but the impact on Wnt signaling or tumor development is unclear." (PMID 31540078, 2019). "The importance of APC in pancreatic cancer is not yet fully understood, and appears complicated depending on the type of pancreatic cancer being assessed." (PMID 31540078, 2019). "This suggests that further investigation into the cell lines is required to uncover the mechanism by which APC status controls proliferation and migration in pancreatic cancer cells." (PMID 31540078, 2019). "In the present study, cellular transfection with siRNA- and shRNA-Fz2 suppressed the proliferation of the MIA-Paca2 cells, a result that we now expect to obtain in patient pancreatic cancer tissues containing normal APC and β-catenin." (PMID 24348824, 2014). "A prior report documented coinheritance of APC and BRCA2 mutations in an individual with FAP and intraductal papillary mucinous neoplasm (IPMN), whose siblings also carrying both mutations developed pancreatic cancer." (PMID 39985003, 2025). "Highly penetrant variants of the APC and BRCA2 genes were also implicated in several rare variant association studies in pancreatic cancer patient families, indicating that they could be potential targets for new associations." (PMID 39858023, 2025). "APC, BRCA2, BUB1B, ENG and MSH6 were associated with cancer predisposition, and pathogenic/likely pathogenic (P/LP) variants occurred in 6% [pancreatic cancer (4/72); all-cancer (5/90)] and 54% (49/90) carried only variants of uncertain significance (VUS) among cancer patients." (PMID 36896836, 2023). "The rates of the APC I1307K variant amongst breast (females only), ovarian, and pancreatic cancer in AJ were not significantly different compared with healthy controls." (PMID 36497357, 2022). "In pancreatic cancer, APC hypermethylation was inferred to result from DNMT upregulation, thus agents targeting DNMT might be possible therapeutic drugs for PC." (PMID 33968756, 2021). "In addition, the possibility of using APC status as either a prediction marker for pancreatic cancer or a tool to determine response to therapy should be explored." (PMID 31540078, 2019).